CD3E (CD3 epsilon subunit of T-cell receptor complex)
Diseases named in the same sentence as CD3E in open-access papers (continued):
Sharing a sentence is not in itself a finding about the gene and the disease.
cancer (77 papers, 2008 to 2026). A tumor composed of atypical neoplastic, often pleomorphic cells that invade other tissues. "Deficiencies of CD3ε have been shown to occur in immunodeficient patients and also in many cancers." (PMID 26497558, 2015). "First and foremost, STAB binding to CD3ε on T cells appear highly effective at redirecting T cells to bind and kill S15+ cancer cells and fibroblasts, as illustrated by our in vitro and in vivo studies." (PMID 40365291, 2025). "Most of the samples from bulk RNA-seq data co-expressed CD19 and CD3E, which is expected as B and T cells are commonly found in tertiary lymphoid structures in various cancers." (PMID 41446065, 2025). "When γδ T cells were co-cultured with cancer cells in the presence of α-GalCer and αCD3e blocker for 24 h, the CD3e blocker completely abrogated the effect of the γδ T cells." (PMID 40801630, 2025). "Unbiased clustering using UMAP identified several cell types, including KRT19+ cancer cells, CD3E+ T cells, MS4A1+ B cells, MZB1+ plasmablasts, FLT3+ dendritic cells (DCs), and PROX1+ LECs, which were then visualized within the tissue context." (PMID 41249124, 2025). "Analysis of the TCGA database demonstrated significant associations between CD3D, CD3E, and CD3G expressions and several cancers, including CC (p < 0.05)." (PMID 40702236, 2025). "Catumaxomab (DB06607) is an agonist of CD3E that facilitates the immune system-mediated destruction of cancer cells." (PMID 38166628, 2024). "Bispecific antibodies that bind to a single HLA-bound peptide surface antigen on cancer cells and an activating T cell antigen such as CD3ε can, through the forced interaction, trigger the lysis of cancer cells." (PMID 38627373, 2024). "We designed two novel TCEs by linking a scFv that recognizes CD3ε on either murine T cells (αCEA:mCD3) or human T cells (αCEA:hCD3) to a His-tagged scFv that binds human CEACAM5 on the surface of cancer cells." (PMID 36405739, 2022). "CD3E expression is upregulated in certain cancer types and it has been recently highlighted as an attractive therapeutic target in cancer." (PMID 36291815, 2022). "Pan-cancer analysis also revealed a positive correlation between LCK/CD3E and TMB in several types of cancers, despite the coefficients being small." (PMID 35004669, 2021). "In line with that, GPR171 expression is well associated with T-cell signature genes CD3e and LCK across multiple cancer types in The Cancer Genome Atlas (TCGA) database." (PMID 34615877, 2021). "In contrast, the increased expression of CD3E was found markedly related to the effective response in 31 cancer types patients who received anti-PD1 immunotherapy." (PMID 33748188, 2021). "To compare TAM infiltration and PD-L1 expression in human GBM versus a wide range of other cancers, we analyzed the TCGA database for mRNA expression of two TAM-associated genes (CD163; PD-L1 [CD274]) and one T cell-associated gene (CD3E)." (PMID 34083417, 2021). "Genes tend to show highly consistent CD3E co-expression patterns across the 31 cancer types studied." (PMID 31360302, 2019). "We generated a heat map to indicate the strength of correlation in expression between each gene in a 40-gene candidate panel and the pan T-cell marker CD3E, across 31 cancer types." (PMID 31360302, 2019). "Typically in the case of bispecific T cell redirection antibodies, the affinity for the cancer cell surface target is much higher (i.e., 10-fold or more) than the affinity for the CD3E chain on T cells." (PMID 28822103, 2018). "Third, OKT3, the first commercial antibody that can bind CD3ε and activate T cells, was chosen as the functional arm of the bispecific antibody, since it has been used in bispecific-antibody designs for cancer and viral therapies (30, –, 33)." (PMID 29038280, 2018). "One of these targets FCGR3A (CD16a) for NK cell redirection, while the other 26 bispecific antibodies target CD3E on T cells to redirect the cytotoxic T cells (CTLs) to kill and lyse cancer cells." (PMID 28822103, 2018).
cancer (continued). "The key new result of the present study is the observation that fusion proteins in the molecular format of single chain triplebodies are also suited for the engagement of cytolytic T cells (CTLs) via CD3ε to eliminate antigen-positive cancer cell targets." (PMID 25115385, 2014). "Here we reveal that the glycosylated K‐TM subunit in T cells and sera of cancer patients is a crucial viral immune checkpoint (VIC) that induces CD8+ T cell anergy via directly targeting CD3ε and disabling TCR signaling and enabling cancer cells to escape immunosurveillance." (PMID 40801282, 2026). "From these clusters, five major cell types were identified via classical cell markers, including T cells (CD3E, CD8A, CD3D), B cells (CD19, MS4A1, CD79A), myeloid cells (CD14, CD68, LYZ), endothelial cells (PECAM1, VWF, CDH5) and cancer-associated fibroblasts (CAFs) (ACTA2, FAP, PDGFRB)." (PMID 39941131, 2025). "In addition, p-blinatumomab specifically targets CD9- and CD3ε-expressing cancer cells, similar to BLINCYTO." (PMID 41168302, 2025). "The 8 cell types were annotated based on the differentially expressed markers: Bnip3 for autophagic cancer cells, Mki67 for proliferating cancer cells, Cd14, Apoe, C1qc, Mrc1, Lyz2 for monocytes, Col3a1 for fibroblasts, Cd3e and Gzma for T cells, Flt1 for endothelial cells, and Klk1 for DCs." (PMID 38802348, 2024). "CD3E tends to show remarkably consistent co-expression patterns across the 31 cancer types." (PMID 37031292, 2023). "Some markers CD14 (monocyte), CD3D (CD4+T cells), CD3E (CD8+T cells), CD68 (macrophage), CST3 (myeloid cells), GNLY (NK cells), KRT18 (epithelial cells), and NKG7 (NK cells) were positively associated with TMSB10 in all cancers." (PMID 37275863, 2023). "Moreover, this positive correlation between memory B cell, CD8+ T cell, CD4+ memory activated, and macrophage M1 with LCK and CD3E was also consistent across different cancer types." (PMID 35004669, 2021). "Interestingly, five genes (CD247, CD3E, ZAP70, LCK, PTPN6) were associated with the hsa05235 pathway (PD-L1 expression and PD-1 checkpoint pathway in cancer)." (PMID 34880861, 2021). "Therefore, some scholars examined the correlation between CD3E expression and putative targets in 9,601 human tumors spanning 31 cancer types." (PMID 34124265, 2021). "The results showed that after HLB-apt treatment, T cell activation markers (CD69, CD3E), interleukin (IL-2), and other cytokines in Jurkat cells were significantly overexpressed (P<0.05), indicating an increase in Jurkat cell killing ability against cancer cells." (PMID 40761795, 2025). "The Nb-TriTE is the first proposed Nb-only candidate to simultaneously target CD3ε, solid tumor site and immune checkpoint, while this Nb-TriTE format differs from previously reported formats, such as TriTE, TriTAC, DARPin, CiTE and other trispecific antibodies for cancer immunotherapy." (PMID 38031188, 2023). "Prognostic correlations between CD3D, CD3E, and CD3G gene expressions and various cancers were analyzed using the Cancer Genome Atlas (TCGA) database." (PMID 40702236, 2025). "Understanding CD3E and CD3G functions offers insights into therapeutic targeting in immune-related diseases and cancer." (PMID 40621499, 2025). "Analysis of cluster-specific genes indicates that these clusters correspond to cancer cells (GFP, Crabp1, Ank), myeloid cells (Aif1, Ctsc, Mpeg1), lymphoid cells (Il2rb, Cd28, Cd3e/g/d, Cd37), and stromal cells (Col1a1/2, Lum, Eln, Dpt), respectively." (PMID 41280683, 2025). "For example, CD3E and CD2 were highly expressed in T cells, CD79A was highly expressed in B cells and KRT18 was highly expressed in cancer cells." (PMID 36681772, 2023). "In 2017, an Fc-free TCE called ATTACK (asymmetric tandem trimerbody for T cell activation and cancer killing) was designed with trivalent and monovalent binding to EGFR and CD3ε, respectively (3 + 1 stoichiometry)." (PMID 36678761, 2022).
cancer (continued). "In multiple dataset validations, CCL5, CXCR6, CD3E and LCK were identified to be down-regulated in cancer tissues." (PMID 34218795, 2021). "Immunohistochemistry results demonstrated that CCL5, CD3E and LCK were expressed at low levels in HCC cancer tissues." (PMID 34218795, 2021). "Combining NPG with HO-1 inhibitor demonstrated down-regulation of genes involved in cancer cell invasion and proliferation (EGR1, CXCL2, AREG, CXCL3, EREG, CD3e, CD3g, CD74, and B2M) as compared to NPG or to control animals." (PMID 34066839, 2021). "In multiple dataset validations, the expression levels of CCL5, CXCR6, CD3E, and LCK were decreased in cancer tissues." (PMID 34218795, 2021). "CD8+ T cells and macrophage M1 are more abundant in favor of a higher expression of CD3E and LCK in MIBC and across pan-cancers." (PMID 35004669, 2021). "The immunohistochemistry results demonstrated that the staining intensity of CCL5, CD3E and LCK in HCC cancer tissues ended to be decreased compared with those in normal tissues." (PMID 34218795, 2021). "Additionally, IL2RB, CD3E, and TBX21 showed significant enrichment in transcriptional misregulation in cancers and Th1 and Th2 cell differentiation pathways." (PMID 39974584, 2025). "In specific, TIS is referred to as an 18‐gene signature (CCL5, GZMK, CD3D, CD3E, CD2, HLA‐DRA, IL2RG, NKG7, CIITA, CXCR6, LAG3, TAGAP, HLA‐E, CXCL13, IDO1, CXCL10, STAT1, and GZMB), which was related to the response to ICIs in various cancers." (PMID 37434432, 2023). "Notably, cells of C8 subgroup were T cell-like cancer cells and expressed specific markers of T cells, such as CD7, CD3D, and CD3E." (PMID 36451812, 2022). "Finally, we extracted the top 20 in-degree and top 20 out-degree genes as the hub nodes of each cancer and identified six co-owned immune feature genes (CD48, GPR65, C3AR1, CD2, CD3E and ARHGAP9) in these cancers." (PMID 35069897, 2022). "Similarly, genes involved in T cell mediated immune response, such as CD3D, CD3E, CD3G, CD247 in the CD3-TCR complex and downstream effector ZAP70, were more rapidly repressed in LUSC than in LUAD, especially at the early cancer stage." (PMID 27863400, 2017). "Thus, p-blinatumomab effectively targets cancer antigens expressed in ALL, such as CD9 and CD3ε." (PMID 41168302, 2025). "Additional potential gene targets are identified that have more highly correlated expression with CD3E than PDCD1 (ranked #55) and CTLA4 (ranked #103) when we expanded the list of studied genes from our 40-candidate list to all genes known to be expressed in cancer." (PMID 31360302, 2019). "Thus, the two top targets, CD19 and CD3E, are responsible for the engineered retargeting of T cells, either as CAR-T cells or T-cell redirecting bispecific antibodies, to kill cancer cells." (PMID 28822103, 2018).
infection (42 papers, 2007 to 2025). The state of being infected such as from the introduction of a foreign agent such as serum, vaccine, antigenic substance or organism. "Infection was also associated with emergence of a population of splenic CD3ε+CD4+ T cells capable of producing both IFNγ and IL-10." (PMID 22911108, 2012). "Having established that MC-deficiency curtails mCMV-induced serum levels of the T and NK/NKT cell-recruiting chemokine CCL5, we quantitated CD3ε+ T cells in absolute terms for comparing infiltration of the lungs on day 6 after intravenous infection of WT C57BL/6 mice and MC-deficient “sash” mutants." (PMID 24763809, 2014). "In the cases of CCL5 and CD3E, these regulatory molecules appear to be dysregulated by these miRNAs during infection, likely contributing further to EVD pathogenesis and fatal outcome." (PMID 33806942, 2021). "IFITM3 KO mice also displayed higher levels of lymphocyte and macrophage recruitment to sites of infection, as judged by CD3e and F4/80 staining of infected tissues, respectively." (PMID 34404769, 2021). "First, our experiments found that Cd3e−/− SD rats that were subject to infection of 100 cercariae per animal for 42 d, also had significantly higher load of worm than the wild-type controls." (PMID 33347431, 2020). "We also compared CD11b+ myeloid cells and B lymphocytes in CD3e−/− B6 mice and wild-type mice following infection, and found that accumulation of such immune cells in liver was markedly decreased when T cells were absent." (PMID 33347431, 2020). "Our qPCR data showed upregulation of both CD3ε and CD3ζ genes at 2 hours which declined at 5 and 24 hours post-infection." (PMID 30923339, 2019). "Upon subsequent infection (day 3), however, CD3e+ T cells are present in higher proportions and total numbers in the spleen in PBS and WCV-immunized mice when compared to ACV-immunized mice." (PMID 30405604, 2018). "We isolated lymph node cells on day 3 of infection, cultured them with anti-IgM and anti-CD3ε for 16 hr, and measured OCR levels in purified B cells after the incubation." (PMID 29249358, 2018). "We also sorted TCRβ+CD3ε−CD11bhighCD14+F4/80+ cells and TCR+CD3ε+ lymphocytes from spleen tissue on day 6 post-infection with Pb−A and compared the size and morphology of these cells by microscopy." (PMID 30044851, 2018). "WCV-immunized mice display proportional decreases in splenic CD3e+ T cells (post-immunization day 3, post-boost day 3, and post-infection day 3 and B220+ B cells (post-boost days 3 and 12)." (PMID 30405604, 2018). "Both TCR (CD3ε gMFI) and co-receptor (CD8α gMFI) levels were unchanged in either the spleen or the brain over the course of infection with MuPyV.TagV or the analogue viruses." (PMID 28410427, 2017). "Infection of donor mice by CMV most likely prime γδ splenocytes to readily respond to CMV once transferred in CD3ε−/− mice, compensating this reconstitution limitation." (PMID 25747674, 2015). "The parasite loads during the acute phase of the infection in CD3ε−/− neonates were similar to those in wild-type neonates." (PMID 24367259, 2013). "During the first 3 days after infection, we noted a substantial increase in the total number of CD3ε+ cells in the lungs." (PMID 22768117, 2012). "When assayed two days post-infection, the highest percentages of hNGFR+ cells were found amongγδT cells, with lower percentages of hNGFR+ iNKT cells and other CD3ε+ cells." (PMID 22768117, 2012). "Western analyses confirmed the expression of CD3ε which increased with time of infection." (PMID 30923339, 2019). "In mice infected with the H1N1 pdm virus, dense staining for CD11c+ dendritic cells was observed in the parafollicular area of CD3ε T-cells (CD3ε+; magenta) throughout the infection period (left), with CD11c+ dendritic cells being particularly abundant until 7 dpi." (PMID 27892498, 2016).
infection (continued). "Interestingly, despite impeded development of adult worms which was in line with previous studies using nude mice, additionally our experiments showed that both worm count and recovery rate of worm in CD3e−/− B6 mice was significantly higher than those in WT mice at 42 d after infection." (PMID 33347431, 2020). "The observed lower expression of T cell associated genes (e.g. IL7R, CD3E, CCR7 and PTPRCv1) in TB patients has been shown previously and might be associated with reactivation of infection and migration of cells to the site of infection." (PMID 31821366, 2019). "We observed that at 7 days post-infection, there was a significant expansion of IL-17A+ cells, including TH17 (CD45+, CD3ε+, CD4+, GFP+) cells." (PMID 37923768, 2023). "After infection, MP antigens stimulate and upregulate T cell surface molecules including CD3D, CD3E, CD3G, and CD8, followed by the upregulation of downstream molecules including CD3Z, FYN, LCK, ZAP70, GADS, P38, and ITK." (PMID 29967623, 2018). "Highly significant decreases in CD3E mRNA were detected in PBMC at 21 dpi (3.1-fold, P = 0.0079 and 3.2-fold, P = 0.0001 in N'Dama and Boran respectively) relative to pre-infection levels, which was sustained throughout the time course." (PMID 19409086, 2009). "As observed following in vivo infection, the addition of HSV-1 to B6 splenocytes rapidly activated NK cells with ∼21% of CD3ε– NK1.1+ cells producing IFN-γ by 8 h." (PMID 17407097, 2007). "Regardless of infection, micefed PD demonstrated a skew toward increased myeloid cells (CD11b+)with reciprocal reductions in T-cells (CD3ε+) among CD45+cells analyzed compared with mice fed the CD-diet." (PMID 28750066, 2017). "In the present study, we demonstrate that SAV-3 infections induce mRNA transcripts of genes including IFN-α and its stimulated genes (ISG) at early time, followed by IFN-γ, TNF-α, IL-12, IL-10, IL-8, CD3ε, CD4, CD8, TCR-α, MHC-I, and MHC-II as the infection progresses." (PMID 23116479, 2012). "Infection by HTLV-I has been shown to ultimately downregulate CD3γ, CD3δ, CD3ε, and CD3ζ gene transcripts leading to a CD3- surface phenotype after 200 days of in vitro infection; however, the sequence of gene loss has not been investigated." (PMID 17822534, 2007). "However, following dexamethasone-induced immunosuppression 4 weeks after infection, only CD3ε−/− mice excreted C. parvum oocysts revealing that the infection was not definitively cured in the absence of functional conventional T cells." (PMID 24367259, 2013). "Strikingly, we found that the infection with HeV and NiV-B did not modify the expression levels of lymphocyte markers (CD2, CD3D, CD3E, CD3G, CD4, CD8A and CD27) in the lung tissue by 5 dpi." (PMID 29538374, 2018).
inflammation (2 papers, 2022 to 2023). Aberrant reaction of the microcirculation characterized by movement of fluid and leukocytes from the blood into extravascular tissues. "IBD mice displayed colonic inflammation associated with weight loss and accumulation of MDSCs in the BM and spleen, which was accompanied by CD247 downregulation in splenic T cells with no change in CD3e expression, indicating chronic inflammation and T cell suppression." (PMID 35396510, 2022).
bacterial infection (1 paper, 2018). "We also examined the changes of CD3ε expression after allo-antigen stimulation and bacterial infection." (PMID 29951063, 2018).
CD3E also shares sentences with these, for which no sentence is quoted: AIDS (2 papers); B cell Lymphoma (2); breast invasive carcinoma (2); celiac disease (2); cutaneous malignant melanoma (2); diabetes (2); head and neck cancer (2); lung squamous cell carcinoma (2); oligodendroglioma (2); acute myeloid leukemia (1); adult T-cell leukemia (1); Alzheimer disease (1); Arthritis (1); ataxia telangiectasia (1); B-cell acute lymphoblastic leukemia (1); bladder urothelial carcinoma (1); Bloom syndrome (1); brain inflammation (1); breast tumors (1); Chlamydia infection (1); chronic myeloid leukemia (1); clear cell renal carcinoma (1); coinfection (1); Crohn disease (1); cutaneous T-cell lymphoma (1); dermatomyositis (1); diffuse large B-cell lymphoma (1); DiGeorge syndrome (1); dilatation (1); endocervical adenocarcinoma (1).
A further 45 diseases each share a sentence with CD3E in 1 paper.